EMILIN1 (elastin microfibril interfacer 1)
Diseases named in the same sentence as EMILIN1 in open-access papers (continued):
Sharing a sentence is not in itself a finding about the gene and the disease.
tumor (35 papers, 2016 to 2026). "First, the structural defects in lymphatic endothelial cells characteristic of EMILIN-1 deficiency, including reduced anchoring filaments and impaired intercellular junctions, create physical gaps that facilitate tumor cell intravasation." (PMID 40643467, 2025). "EMILIN-1 deficiency results in increased tumor burden, particularly high-grade adenomas, and enhanced tumor growth." (PMID 40643467, 2025). "This relationship is exemplified in the colon, where EMILIN-1 deficiency exacerbates tumor development through combined effects of lymphatic dysfunction and chronic inflammation." (PMID 40643467, 2025). "This enrichment likely reflects tumor-associated proteolytic processing of EMILIN-1, consistent with the inactivation mechanisms observed in solid tumors." (PMID 40643467, 2025). "EMILIN1 is closely associated with elastic fibers, known to be involved in skin homeostasis and carcinogenesis, affecting on tumor cell proliferation and lymph node invasion." (PMID 38184660, 2024). "EMILIN-1 deficiency causes lymphatic hyperplasia and structural anomalies, facilitating lymphangiogenesis-related tumor cell dissemination to LNs." (PMID 28036019, 2016). "EMILIN1 associates with elastic fibers, influencing tumor development." (PMID 39958347, 2025). "This tumor-suppressive capacity suggests that EMILIN-1-deficient microenvironments may foster tumor development." (PMID 40643467, 2025). "Interestingly, the decreased EMILIN-1 levels in tumor tissue associated with the presence of morphologically aberrant podoplanin-positive LVs." (PMID 38941035, 2024). "Our aim was to understand whether EMILIN1 loss influenced this aspect of the mammary microenvironment and whether the earlier tumor onset seen in Δ16HER2/EMI1 KO mice could, in part, be attributed to altered ECM stiffness." (PMID 38184660, 2024). "Although this finding could be influenced by variations in stromal content in healthy versus tumor samples, we found an even more pronounced loss of EMILIN1 expression in metastatic specimens." (PMID 38184660, 2024). "We expect that a more comprehensive exploration of the mechanism and implications derived from the loss of interaction between EMILIN1 and α4/α9β1 integrins, will provide us with a more profound understanding of the role played by basal membrane disruption in tumor initiation." (PMID 38184660, 2024). "This review article provides a comprehensive analysis of the recently discovered mechanisms through which EMILIN-1 promotes tumor progression in the nervous system and other sites." (PMID 41994657, 2026). "As an underappreciated modulator of tumor biology, EMILIN-1 presents exciting opportunities for innovative cancer interventions." (PMID 40643467, 2025). "Similar patterns of EMILIN-1 downregulation are observed in bladder, lung, ovarian, rectal, and uterine carcinomas, supporting its potential tumor-suppressive function across multiple cancer types." (PMID 40643467, 2025). "Specifically, elevated EMILIN-1 expression at the tumor margins correlated with enhanced cytotoxic T-cell recruitment, attenuation of TGF-β-mediated immunosuppression and improved patient prognosis." (PMID 40643467, 2025). "The functional characterization of EMILIN-1 in proliferation and tumor suppression has been largely achieved through the Emilin1−/− and E1-E955A mouse models." (PMID 40643467, 2025). "Proteomic analyses reveal elevated EMILIN-1 levels in serum-derived EVs from mucinous colon adenocarcinomas (a clinically aggressive subtype), suggesting either compensatory tumor-suppressor mobilization or pathologic co-option of vesicular transport." (PMID 40643467, 2025). "EMILIN-1 (Elastin Microfibril Interface Located Protein 1) is an extracellular matrix homotrimeric glycoprotein belonging to the EMILIN/Multimerin family, with both structural and regulatory roles, increasingly recognized for its tumor-suppressive functions." (PMID 40643467, 2025).
tumor (continued). "As mentioned, the functional role of EMILIN-1 in cancer appears to be highly context-dependent, with both tumor-suppressive and tumor-promoting activities observed across different malignancies." (PMID 40643467, 2025). "EMILIN-1 has emerged as a pleiotropic ECM glycoprotein whose tumor-suppressive functions substantially transcend its canonical structural role." (PMID 40643467, 2025). "In the colon, the EMILIN-1 tumor-suppressive mechanism during chemically-induced carcinogenesis involves the suppression of AKT and ERK activation." (PMID 40643467, 2025). "The TCGA database analysis showed higher expression of EMILIN1 in 520 HNSCC tumor tissues compared to 44 normal epithelial tissues." (PMID 39892781, 2025). "Such discrepancies suggest that EMILIN-1’s functional relevance is influenced not only by the tumor cell type but also by the composition of the TME and stromal interactions." (PMID 40643467, 2025). "Second, the enhanced lymphangiogenesis observed in both primary tumors and sentinel LNs of EMILIN-1 mutant mice establishes an expanded network of conduits for tumor cell dissemination." (PMID 40643467, 2025). "In conclusion, this study provides evidence that EMILIN-1 exerts tumor suppressive effects in HNSCC." (PMID 39892781, 2025). "Immunohistochemical analysis in HNSCC tissues demonstrated that EMILIN-1 predominantly localized in the tumor cell surrounding." (PMID 39892781, 2025). "Overall, these studies on EMILIN-1′s tumor-suppressive mechanisms highlight its role not only as a non–cell-autonomous regulator within the TME but also as an active modulator of cellular behavior." (PMID 40643467, 2025). "A tumor-suppressive role has been observed upon epigenetic silencing via promoter hypermethylation, which reduces EMILIN-1 expression in fusion-positive rhabdomyosarcoma and uterine carcinosarcoma, particularly in carcinomatous components." (PMID 40643467, 2025). "In this regard the current study highlights EMILIN1 as an important determinant of CAF anti-tumor program." (PMID 38505604, 2024). "The tumor-suppressive function of EMILIN-1 was corroborated also through the intraperitoneal injection of YTN16 cells in transgenic mice." (PMID 38941035, 2024). "Our results are in line with previous data and suggested a tumor suppressive role for EMILIN1 in BC, as already seen in other contexts." (PMID 38184660, 2024). "Consistently, when tumor masses were separated from the surrounding stroma, EMILIN1 transcription was detected essentially in the stromal compartment while the tumor component expressed only negligible levels." (PMID 38184660, 2024). "This accelerated tumor initiation was corroborated by an increased number of tumor foci observed in mammary glands from Δ16HER2/EMILIN1 KO mice compared to the wild-type counterpart." (PMID 38184660, 2024). "The results confirmed that both CYFIP1 and EMILIN1 were upregulated in tumor tissues, and the knockdown of these two genes affected various tumor phenotypes in NB cells, including colony formation, migration, and invasion." (PMID 38427078, 2024). "A functional link between ECM protein EMILIN-1, tumor growth and lymphangiogenesis has been extensively demonstrated in different tumor models." (PMID 38941035, 2024). "Additional analysis in restricted number of EMILIN1-high cases showed that many CD8+ T cells infiltrating in the tumor were Ki-67 positive (yellow arrowheads)." (PMID 38505604, 2024). "The analyses of inflammatory infiltrates also showed a correlation between lymphatic dysfunction and tumor growth due to decreased EMILIN-1 levels." (PMID 38941035, 2024). "The study of the EMILIN1 KO mouse model reinforced those notions, suggesting a protective role of EMILIN1 in tumor growth and, possibly, in the metastatic spread to lymph nodes." (PMID 38184660, 2024). "Tissue immunohistochemistry revealed an upregulation in the expression of CYFIP1 and EMILIN1 in tumor tissues compared to adjacent normal tissues." (PMID 38427078, 2024).
tumor (continued). "EMILIN1, an extracellular matrix glycoprotein, is proposed to play a role in tumor progression and invasion in LGG." (PMID 38955935, 2024). "The precise mechanism behind this tumor initiation phenotype has still to be fully elucidated, but our data indicate a dependency on the interaction between the gC1q domain of EMILIN1 and the α4/α9β1 integrins." (PMID 38184660, 2024). "We next analyzed the effect of EMILIN-1 overexpression in tumor growth and metastatic properties of B16-F1 cells." (PMID 34299025, 2021). "Studies with the knock-out animal revealed an important role of EMILIN-1 in the microenvironment to prevent tumor growth and spontaneous metastasis models." (PMID 34299025, 2021). "Higher expression levels were found in the tumor tissues than in the corresponding normal tissues, except for EMILIN1 and MMP2." (PMID 35071018, 2021). "In our study of EMILIN1, we observed significant links to tumor grades, overexpression in LGG and correlation between high-expression levels and poor OS and DFS." (PMID 32175193, 2020). "The extracellular secretory protein EMILIN1 can increase this tumor suppressive effect by promoting the expression of TSPAN9." (PMID 31242895, 2019). "All these results suggested that the synergistic anti-tumor effects of EMILIN1 and TSPAN9 are achieved by increasing the expression level of TSPAN9." (PMID 31242895, 2019). "EMILIN-1 structural integrity represents a regulator of fundamental processes, e.g., tumor phenotype and dormancy, and premetastatic niche formation." (PMID 28036019, 2016). "In HNSCC, although increased EMILIN1 expression was observed in tumor tissues, post-translational modifications of EMILIN-1 could have a greater impact on creating a TME that promotes cell proliferation." (PMID 39892781, 2025). "This suggests that while EMILIN-1 gene expression may be elevated, proteolytic processing by tumor or microenvironment-derived enzymes could render the protein non-functional." (PMID 40643467, 2025). "Furthermore, using the in vivo CAM assay with FaDu cells, EMILIN-1–overexpressing tumors exhibited significant reductions in tumor growth and Ki-67–positive proliferative cells, along with an increase in the CC3-positive apoptotic cancer cells." (PMID 39892781, 2025). "While few pathogenic EMILIN-1 mutations have been identified in humans, those reported occur in regions outside N- and C-terminus domains and, therefore, do not affect its tumor regulatory properties." (PMID 40643467, 2025). "Furthermore, in an in ovo chick chorioallantoic membrane model, overexpression of EMILIN-1 in FaDu cells reduced tumor size and Ki-67–positivity and increased cleaved caspase-3–positive cells." (PMID 39892781, 2025). "An association between EMILIN-1 and cancer suggests that this ECM glycoprotein could play a tumor-suppressive role in the tumor microenvironment (TME) by regulating cell growth and cell migration." (PMID 39892781, 2025). "EMILIN1 levels were higher in HPV-negative HNSCC tumor tissues than in HPV-positive ones." (PMID 39892781, 2025). "EMILIN-1 expression may appear upregulated in certain tumors; however, its tumor-suppressive activity depends on its functional integrity and interaction with specific integrins." (PMID 40643467, 2025). "This process reduces intracellular EMILIN-1 levels, may represent an early metastatic adaptation, and parrales known tumor-suppressor elimination pathways." (PMID 40643467, 2025). "The preliminary data on MMP expression and the presence of neutrophil elastase in tumor tissue suggest that the decreased EMILIN-1 levels may be due to both transcriptional and enzymatic processes." (PMID 38941035, 2024). "Collectively, the findings of the present study suggest that tumor-suppressive function of EMILIN-1 may be abrogated by multiple mechanisms in the context of GC, ultimately contributing to tumor growth and possibly cancer spread via the aberrant lymphatics." (PMID 38941035, 2024).
tumor (continued). "This possibility was also confirmed by the observation that EMILIN1 RNA levels progressively decreased in the weeks preceding tumor onset, suggesting that its expression needed to be reduced to facilitate the tumor initiation process." (PMID 38184660, 2024). "Based on these findings EMILIN1 was proposed as a tumor suppressor." (PMID 35739492, 2022). "However, the poor prognostic effect of EMILIN11 and TSPAN9 was surprising since EMILIN-1 is regarded as a tumor suppressor which acts synergistically with TSPAN9." (PMID 35739492, 2022). "We found that EMILIN-1 overexpression led to a significant reduction of tumor growth." (PMID 34299025, 2021). "Interestingly, we observed that EMILIN-1 has intrinsic tumor and metastasis suppressive-like properties reducing effective migration, cell viability, primary tumor growth, and metastasis." (PMID 34299025, 2021). "Notably, we observed a significant decrease in tumor growth in B16-F1 cells overexpressing EMILIN-1." (PMID 34299025, 2021). "The main functions of EMILIN1 include cell adhesion and migration in tumor growth." (PMID 32175193, 2020). "We have herein confirmed the role of EMILIN1 in inducing tumor migration and invasion." (PMID 31242895, 2019). "Finally, the analyses of EMILIN-1 revealed that in some cases tumor samples were characterized by an altered organization of the molecule in the lamina propria." (PMID 30544909, 2018). "The elastin microfibril interface-located protein 1 (EMILIN-1), an extracellular matrix glycoprotein, is diffusely expressed in several tissues, exerting a suppressive or protective role in lymphatic formation, and tumor growth and metastatic spread to LNs." (PMID 28036019, 2016). "Furthermore, ECM components, such as collagen isoforms, Fibrillin-1, EMILIN-1, Prolargin, and Lumican, were found to be highly expressed in the MLH1/PMS2-deficient tumor area, suggesting a connection between DNA repair deficiencies, ECM remodeling, and tumor progression." (PMID 40076915, 2025). "Therefore, higher expression of EMILIN1 in TCGA-HNSC tumors may partly be explained by the high proportion of fibroblasts present in the bulk tumor volume." (PMID 39892781, 2025). "Therefore, EMILIN-1 should not be regarded as a universal hallmark of tumor biology but rather as a context-specific regulator whose significance varies with tissue type, cellular milieu, and potential tumor stage." (PMID 40643467, 2025). "Moreover, EMILIN1 can synergistically boost the tumor suppressive effect of TSPAN9, which may be produced by promoting TSPAN9 expression." (PMID 31242895, 2019). "Recent experimental data highlight the importance of EMILIN-1 in cancer biology, especially in malignant tumors of the nervous system, where EMILIN-1's regulatory functions influence tumor progression and metastatic potential." (PMID 41994657, 2026). "Contrary to its potential role as a candidate tumor suppressor, TCGA-HNSC data showed higher EMILIN1 expression in tumors compared with normal epithelial tissues." (PMID 39892781, 2025). "The reciprocal effects observed between EMILIN-1 knockdown and EMILIN-1–overexpressing cells suggest a potential tumor suppressor role in HNSCC." (PMID 39892781, 2025). "Previous studies have reported decreased EMILIN1 expression in metastatic BRCA tumors, suggesting a potential tumor-suppressive role." (PMID 39958347, 2025). "The relationship between the structural integrity of EMILIN-1 and functional properties of LVs was further defined when we treated mice with MNU, a potent carcinogen whose efficiency in tumor induction is fairly low according to the literature." (PMID 38941035, 2024). "Others such as EMILIN1 and HSPG2 were expressed in both tumor and adjacent normal tissue and, thus, unsuitable for selective targeting of malignant tissue." (PMID 37098922, 2023). "Moreover, EMILIN1 could promote the tumor-suppressive effect of TSPAN9." (PMID 35600044, 2022).
tumor (continued). "Based on this, we next analyzed the effect of the stabilization mutant of EMILIN-1 (E1-R914W) in B16-F1R2 cells in primary tumor growth and metastasis." (PMID 34299025, 2021). "In summary, in the present study we highlighted the roles of EMILIN1 and TSPAN9 in tumor cell regulation and the mechanisms involved in TSPAN9-mediated cell migration and invasion." (PMID 31242895, 2019). "Although EMILIN-1 frequently appears in cancer-related gene expression signatures and is often characterized as a tumor suppressor, its expression does not consistently correlate with malignant progression." (PMID 40643467, 2025). "Extensive research has demonstrated that this regulatory activity defines EMILIN-1 as a non-conventional ECM component with tumor-inhibitory capacity across various cancer types." (PMID 40643467, 2025). "Although EMILIN-1 does not fit the classical definition of a tumor suppressor based on genetic inactivation, its tumor-suppressive properties arise from non–cell-autonomous mechanisms, primarily through modulation of the tumor microenvironment." (PMID 40643467, 2025). "In fact, we were able to detect five upregulated proteins in the normal mucosa adjacent to the tumor, namely laminin subunit alpha-4 (LAMA4), elastin microfibril interfacer 1 (EMILIN1), LTBP1 and fibrinogen beta chain (FGB), as well as proteoglycan versican core protein (VCAN)." (PMID 35340765, 2022). "In addition, the ACTA2, ASPN, PDGFRB, PDPN, COL12A1, EMILIN1, and CDH11 genes were upregulated in CAFs of several tumor types." (PMID 36263012, 2022). "We observed that while EMILIN-1 stabilization mutant did not affect significantly primary tumor growth, it reduced significantly spontaneous lymph node metastasis." (PMID 34299025, 2021). "Since the expression level of TSPAN9 in tumor cells is lower than that of normal cells, simply increasing the expression of EMILIN1 in tumor cells does not promote the expression of TSPAN9." (PMID 31242895, 2019). "These analyses indicated that EMILIN-1 levels did not change considerably in the tumor samples, despite the organization of the molecule was altered in some samples." (PMID 30544909, 2018). "These genes likely function as downstream effectors of STAT3 in GBM to regulate not only cell proliferation (e.g., GAS7, IGFBP2, MEOX2 and MXI1), and but also tumor-stroma interactions by modulating protein secretion (e.g., ANXA1, ARL4C, EMILIN1, EMP2, EXTL3 and PDIA4)." (PMID 29774125, 2018). "The absence of EMILIN-1 induces cell proliferation and tumor growth in skin tumors." (PMID 39892781, 2025). "Two additional members of this family, Emilin1 and Emilin2, resulted enriched in their respective AAV9-pool, and scored high in the final ranking (33rd and 77th position, respectively), confirming a relevant role of these ECM proteins in inhibiting tumor invasiveness." (PMID 38195652, 2024). "Remarkably, analysis of another dataset that included GC at different stages showed no variations in EMILIN-1 expression, suggesting that its levels could be particularly critical in the early phases of the disease but irrelevant during tumor progression." (PMID 38941035, 2024). "Therefore, we believe that the synergistic anti-tumor effect of EMILIN1 and TSPAN9 is mainly achieved by TSPAN9.We further found that simultaneous overexpression of EMILIN1 and TSPAN9 more significantly inhibited the FAK-RAS-ERK1/2 pathway as compared to the overexpression of TSPAN9 alone." (PMID 31242895, 2019). "Indeed, only one patient with a T1b stage displayed lower EMILIN-1 levels in the tumor compared to the adjacent normal mucosa, whereas EMILIN-1 expression did not change in patients with a T3 stage grading (C and data not shown)." (PMID 30544909, 2018). "Therefore, we speculate that EMILIN1 itself does not play a major role in tumor suppression, but through synergy with TSPAN9 to exert a anti-tumor effect." (PMID 31242895, 2019).